INS (insulin)
Diseases named in the same sentence as INS in open-access papers (continued):
Sharing a sentence is not in itself a finding about the gene and the disease.
Obesity (continued). "Weight loss in individuals with obesity was associated with improvements in insulin sensitivity and blood lipid profiles and a significant reduction in tissue Ki‐67 expression." (PMID 29086510, 2017). "Leptin and adiponectin play an important role in obesity-associated metabolic risk by modulating inflammatory processes and affecting insulin sensitivity." (PMID 28077136, 2017). "To ascertain the putative causal relationship between presence of BCa and impaired glucose/insulin metabolism, we have determined the circulating levels of obesity- and BCa-associated factors." (PMID 29113405, 2017). "Physical exercise has been recognized as a key positive modulator of obesity associated metabolic pathways such as insulin signalling and inflammation." (PMID 28264047, 2017). "Palmitic acid in adipose tissue is negatively associated with insulin sensitivity, suggesting that changes induced by obesity surgery and following dietary changes are beneficial." (PMID 28869586, 2017). "The increased obesity in the offspring of high carbohydrate-fed dams was linked with a 3-fold increase in fasting levels of insulin." (PMID 28684678, 2017). "Our results show a novel role of the VD system in the regulation and activation of IGFBP-3 in visceral adipose tissue (VAT) of patients with MO, as a new and alternative mechanism proposed in the insulin signaling associated with obesity." (PMID 29112142, 2017). "It is also well known that bariatric surgery improves the main defects responsible for obesity-associated hyperglycaemia, namely insulin resistance and beta-cell dysfunction." (PMID 28966594, 2017). "Chronic, low-grade inflammation plays a causal role in the loss of insulin sensitivity of adipose tissue; adipose tissue inflammation and dysfunction link obesity to the pathogenesis of type II diabetes." (PMID 29018280, 2017). "In consistency with the observations in the case-control study, in this study, PC2-Z was associated with obesity (OR = 1.18; 95%CI 1.05–1.34, P = 9.3 × 10−3), BMI percentile, fat mass percentage, insulin, and TG and levels (all P < 0.05)." (PMID 28717206, 2017). "Specifically, mounting evidence indicate that several obesity-associated factors such as insulin, leptin, adiponectin or triglycerides can contribute to the development and/or progression of several cancer types, including BCa." (PMID 29113405, 2017). "To date, there are no published clinical studies comparing protein levels or gene expression of IGFBPs and related proteins in VAT or between the insulin-sensitive and insulin-resistant associated with obesity." (PMID 29112142, 2017). "In this review, we focus on obesity-associated changes in inflammation, metabolism, and impaired insulin signaling, which are pathologically dysregulated and ultimately result in a loss of muscle mass and function." (PMID 28261159, 2017). "Obesity associated hyperglycemia has also been shown to reduced surface expression of hERG channel subunits and hERG1/IKr density which is rescued by insulin, suggesting that ROS is an important regulator of hERG1/IKr functional expression." (PMID 28680407, 2017). "Our analysis found maternal cafeteria‐style diets led to greater offspring body weight, whereas diet‐induced obesity was associated with increased offspring lipids and insulin concentrations." (PMID 28371083, 2017). "Together, these evidences suggest that cats inherently have lower ability to process GLU, are predisposed to obesity and INS resistance, and to visceral obesity-induced lipid metabolism abnormality just as in humans." (PMID 28261588, 2017). "A decrease in plasma levels of C14:0 ceramide was associated with changes in insulin-stimulated glucose disposal (r = −0.56; P < 0.01) in adult subjects with obesity or type 2 diabetes (T2D)." (PMID 28634575, 2017). "Nonetheless, the GIP variants directly linked to obesity or insulin dysfunction are less well characterized." (PMID 28530680, 2017).
Obesity (continued). "Acetate has also been reported to stimulate insulin secretion and related changes associated with obesity and metabolic syndrome." (PMID 28245817, 2017). "The purpose of the present study was to examine the effects of the artificial sweetener, rebaudioside A (Reb-A), on circadian rhythms, in vivo insulin action, and the susceptibility to diet-induced obesity." (PMID 28475596, 2017). "That defective insulin clearance contributes significantly to these obesity-associated metabolic abnormalities has been demonstrated in several species, including humans." (PMID 28396653, 2017). "In response to physical activity, muscles release bioactive peptides, namely, myokines, which stimulate muscle growth and hypertrophy, enhance insulin sensitivity, and thereby, protect against obesity-associated metabolic abnormalities." (PMID 28721400, 2017). "Intrahepatic diacylglycerol content is negatively associated with hepatic insulin sensitivity in patients with NAFLD complicated by obesity." (PMID 29037210, 2017). "Dysfunctional insulin signaling and anomalous AT expansion result in a lipid spillover inducing peripheral lipotoxicity, which is partially causative of obesity complications." (PMID 29242563, 2017). "The relationships among obesity-associated metabolic disturbances, insulin sensitivity, and circulating irisin levels have been investigated in both rats and humans." (PMID 28077341, 2017). "We show that the deletion of a single allele of p32 is sufficient to produce resistance to obesity and prolong the sensitivity of mice to insulin." (PMID 28720899, 2017). "On the other hand, this inflammatory response is also a key factor for modulating insulin sensitivity in adipose tissue and the development of obesity-associated diseases." (PMID 28445389, 2017). "Weight loss can improve obesity-related diseases such as hypertension and abnormal lipid metabolism, reduce the serum insulin level, and improve insulin sensitivity." (PMID 29234438, 2017). "The A allele increases the risk of obesity and systolic BP and reduces insulin level in patients with metabolic syndrome." (PMID 28852433, 2017). "Reducing visceral fat improved hepatic insulin action and reduced expression of excessive inflammatory cytokines, as visceral fat was considered as a key factor for obesity-associated diseases." (PMID 28264489, 2017). "Whereas those animals impaired in octß1r, octß2r and tar1 share the obesity phenotype of OA-deficient (tβh-deficient) animals, the octß1r, octß2r deficient flies showed reduced insulin release, which is opposed to the situation found in tβh-deficient animals." (PMID 28878633, 2017). "In summary, HCFD feeding causes obesity, increased visceral adiposity, hyperglycemia, reduced glucose tolerance and insulin resistance in both genders." (PMID 28797077, 2017). "Obese individuals with a higher baseline relative abundance of A. muciniphila tend to have greater improvements in obesity-associated metabolic parameters (insulin tolerance, plasma triglycerides and body fat distribution) after dietary intervention." (PMID 28388917, 2017). "Obesity is associated with resistance to the biological effects of both insulin and the satiety hormone leptin." (PMID 28360931, 2017). "Conversely, PA interventions decrease inflammation, increase insulin sensitivity, and decrease risk for a similar set of diseases (e.g., see Ertek and Cicero, 2012), suggesting that the mechanisms underlying obesity and PA converge." (PMID 28507516, 2017). "Several miRNAs, such as miR-132, miR-155, miR-130, miR-145, miR-146b, and miR-29 have been indentified in obesity-associated inflammation and insulin-resistance in adipocytes." (PMID 29050301, 2017). "Upregulation of iNOS has been clearly implicated in obesity and diabetes, and NO overproduction induced by high-fat diet was reported to downregulate the insulin signaling in skeletal muscle, white adipose tissue and liver." (PMID 29229986, 2017).
Obesity (continued). "In rare cases of obesity due to leptin deficiency, the administration of human recombinant leptin leads to an apparent increase in insulin sensitivity, possibly associated with a rapid weight loss." (PMID 28626772, 2017). "Further studies are required to clarify these mechanisms and establish causal effects of systemic inflammation and obesity on insulin sensitivity and resistance, especially in humans." (PMID 28575103, 2017). "Specifically, physical inactivity and high-fat diet, as modifiable factors for obesity, increase insulin levels and IR, and are associated with increased risk of breast cancer and CRC." (PMID 28446149, 2017). "We observed that the prevalence of obesity steadily increased across SUA quartiles, and SUA levels tightly and independently related to obesity in T2DM even after controlling for other obesity risk factor, such as age and use of insulin." (PMID 28051185, 2017). "On the other hand, while it is evident that Asian populations are more insulin resistant than other ethnic groups, in spite of less obesity, it is necessary to better identify the factors underlying the interethnic differences." (PMID 28287627, 2017). "Accumulating evidence from clinical and animal studies suggests that obesity-associated molecules including leptin, insulin, IGF-1, and adiponectin influence the development of colonic diseases." (PMID 28170448, 2017). "Abnormalities in PPARγ expression has been found to be associated with the loss of insulin sensitivity in obesity and Type2 diabetes indicating insulin regulation of PPARΥ expression." (PMID 28072841, 2017). "In summary, this study identifies novel genes associated with insulin sensitivity in adipocytes in women independently of obesity." (PMID 28570579, 2017). "Adipose tissue angiogenesis and vascular functions have long been associated with obesity, adipose metabolism, and insulin sensitivity." (PMID 28848738, 2017). "The largest network included 20 proteins and was predicted to be involved in tissue morphology, inflammatory response and cardiovascular diseases including proteins encoded by genes already associated with obesity (INS, LEP, SERPINE1, IL1RAP, and RARRES2)." (PMID 29234017, 2017). "Increased irisin levels have been proposed to serve as an adaptive response that compensates for the decreasing insulin sensitivity and metabolic disturbances associated with obesity." (PMID 28077341, 2017). "Obesity, sedentary lifestyle and aging are associated with mitochondrial dysfunction and impaired insulin sensitivity." (PMID 29161316, 2017). "Post-intervention TMAO excretion was anti-correlated with obesity traits and was associated with a reduction of the expression of key enzymes involved in energy metabolism, lipid biosynthesis, and insulin signaling in adipose tissue." (PMID 28683308, 2017). "The pattern by which genetic variants interact as well as the modifying role of insulin appears different between normal individuals and individuals with obesity, which can be informative about biological function in further." (PMID 28530680, 2017). "Previous research showed that vaspin was associated with obesity and glucose metabolism, and administration of vaspin in obese mice improved glucose tolerance and insulin sensitivity and reduced food intake." (PMID 28553648, 2017). "Basal SNS activity measured by MSNA was closely associated with liver insulin sensitivity in men with obesity." (PMID 28293196, 2017). "Resistance to the action of insulin resulting from obesity causes downregulation of adiponectin receptors in muscle and liver." (PMID 29412387, 2017). "Our findings that sedentary adult Atg7h&mKO mice became as obese and insulin resistant as control mice contrasts with a previous study, where skeletal muscle-specific loss of Atg7 was protective against obesity and insulin resistance." (PMID 28801668, 2017).
Obesity (continued). "As expected, despite a standard postnatal diet the adult male offspring developed obesity associated with increased caloric intake, as well as reduced insulin sensitivity, increased plasma leptin and triglyceride levels, and higher systolic blood pressure." (PMID 28717143, 2017). "Adipose tissue expansion, a hallmark of obesity, is linked to chronic low-grade inflammation and increased secretion of adipokines which increase insulin-resistance." (PMID 28704534, 2017). "When identifying causes of the high fasting glucagon and insulin levels, circulating free fatty acids (FFAs) have been considered since they are elevated in obesity and such elevation is associated with an increased risk of developing T2DM7." (PMID 28680093, 2017). "Obesity-associated tissue inflammation is now recognized as an important cause of decreased insulin sensitivity." (PMID 28692672, 2017). "The present study identified specific associations between 10 AAs and the type/degree of obesity, and indices of glucose/insulin regulation, in Japanese adults with preserved glucose metabolism." (PMID 26788116, 2016). "Resistance to the actions of leptin or insulin is associated with the pathophysiology of obesity and type 2 diabetes." (PMID 27812350, 2016). "Fractalkine (Cx3cl1) is a chemokine, that was recently implicated in diet induced obesity, insulin regulation and promotion of hypothalamic inflammatory response to fatty acids." (PMID 27623010, 2016). "Potential mechanisms for this link include increased estrogen production by adipose tissue, crosstalk between insulin or insulin-like growth factor and estrogen receptor signaling, obesity-associated hyper-methylation, and tumor growth-promoting adipokines." (PMID 27798667, 2016). "reveal the potential consequences of chronic AMPK activation in mice carrying an activating γ2 mutation, which results in obesity, hyperphagia, and impaired insulin secretion." (PMID 27133129, 2016). "A key area of focus for research into the obesity-cancer connection is the role of the increased insulin levels that are associated with obesity." (PMID 27604692, 2016). "So in the pathogenesis of AN, obesity causes increased insulin levels which further leads to increased IGF-1 receptor activation and contributes to hyperkeratosis." (PMID 27190511, 2016). "Chronic low-grade inflammation in obesity and impaired insulin sensitivity has been associated with fewer Tregs in adipose tissue." (PMID 27478850, 2016). "MetS components, in particular obesity and lipid indices, as well as serum insulin levels, mediate the association between adiponectin and MetS as defined by both the IDF and AHA/NHLBI criteria." (PMID 27567677, 2016). "Obesity has been found to be associated with anovulatory infertility due to the changes in sensitivity to insulin and androgen which affects hormonal milieu." (PMID 27738654, 2016). "Obesity-associated T2D is generally thought to result from the inability of pancreatic islets to secrete sufficient insulin to compensate for the increased insulin resistance of peripheral tissues." (PMID 27043434, 2016). "In an alternative model of genetic obesity, LXRα/β-deficient ob/ob mice remain obese and have increased adipose lipid storage, but display reduced hepatic lipid accumulation and improved insulin sensitivity compared to ob/ob mice." (PMID 26611207, 2016). "Obesity is also associated with increase in body’s energy requirement hence the associated increase in blood glucose and saturated fatty acids and possibly insulin resistance." (PMID 27871259, 2016). "It has recently been shown that heterozygous endoglin deficiency in mice decreases insulin secretion in an animal model of obesity, highlighting a potential role for endoglin in the regulation of islet function." (PMID 27456002, 2016). "Increased peripheral chemosensitivity (PChS) has been proposedas mechanism underlying obesity-related sympathoactivation, with insulin and/or leptin as possible mediators." (PMID 26781642, 2016).
Obesity (continued). "Vaspin is an adipokine that is predominantly secreted by Visceral Adipose Tissue and its serum levels are increased and associated with obesity and impaired insulin sensitivity." (PMID 27721574, 2016). "Impaired placental insulin signaling is associated with obesity, gestational diabetes mellitus, or intrauterine growth restriction (IUGR)." (PMID 26925174, 2016). "This study aims to evaluate glycaemic profiles in children with overweight and obesity in free-living conditions, and to examine the association between glycaemic profiles with insulin resistance and cardiovascular risk parameters." (PMID 27534260, 2016). "sPLA2-IB, a pancreatic sPLA2 that is secreted into the GI lumen, hydrolyzes dietary and biliary phospholipids to promote lipid digestion and absorption, which is associated with obesity and hepatic insulin resistance." (PMID 29259680, 2016). "Thepolymorphisms evaluated in this study are associated with obesity in Afro-Americans andwith increased BMI, waist circumference, fasting insulin levels and skin fold thicknessin Mexicans living in USA (Richardson etal., 2006; Sutton etal., 2005)." (PMID 27560839, 2016). "Still, in both species, resistin is elevated in obesity, regulates insulin sensitivity, and is positively associated with insulin resistance and glucose tolerance." (PMID 27379019, 2016). "Obesity was recently associated with hypermethylation of gene loci involved in inflammation, insulin signaling, and leptin signaling in normal breast tissue from cancer-free women." (PMID 27338371, 2016). "Literature also shows physical inactivity is associated with increase in the risk of obesity by increasing the amount of saturated fatty acids in the body and hence triggering insulin insensitivity." (PMID 27871259, 2016). "Further studies found significant associations of the variants with obesity-related traits and also with fasting insulin and insulin sensitivity." (PMID 27312935, 2016). "Together, these studies indicate that JNK1 and JNK2 play important roles in metabolic stress responses by causing insulin resistance in peripheral tissues and promoting obesity by suppressing energy expenditure." (PMID 26910012, 2016). "Although adiponectin is exclusively secreted from adipocytes, it is a circulating hormone whose level in plasma is positively correlated with insulin sensitivity and inversely associated with obesity and T2D." (PMID 27553852, 2016). "Obesity is associated with increased ceramide content in muscle which coincides with reduced insulin stimulated Akt phosphorylation." (PMID 27128935, 2016). "Elevated plasma FFA levels, affected also by diet and exercise and resulting from obesity or high-fat feeding, can cause insulin resistance, as well as low-grade inflammation." (PMID 27973438, 2016). "In humans, Pten mutations have been described as a cause of constitutive insulin sensitivity and obesity." (PMID 27893783, 2016). "Three hormonal mechanisms have been proposed to play a causative role for an increased cancer risk in obesity: sex hormone metabolism, insulin and insulin-like growth factor (IGF) signaling, and adipokines." (PMID 27893783, 2016). "Obesity is typically associated with organismal insulin resistance, a systemic condition whereby tissues fail to respond to insulin." (PMID 27604692, 2016). "Obesity and type 2 diabetes are characterized by reduced fecal microbial diversity which is linked to increased inflammation and decreased insulin sensitivity." (PMID 26956847, 2016). "For example, increased susceptibility to diet-induced obesity, altered insulin signalling, hyperglycemia and/or glucose intolerance have been reported in a number of clock gene mutant or knockout mouse lines (e.g.5, 41, 49)." (PMID 27439882, 2016). "Collectively, our data suggest that in subjects with visceral fat obesity, endothelial function is impaired by multiple cardiovascular risk factors exclusively when under the condition of insulin insensitivity." (PMID 27188597, 2016).